AR (androgen receptor)
Diseases named in the same sentence as AR in open-access papers (continued):
Sharing a sentence is not in itself a finding about the gene and the disease.
bladder cancer (continued). "ERα, ERβ, and the androgen receptor (AR) are also thought to play a role in bladder cancer development and progression." (PMID 30343668, 2018). "Of note, we recently showed a functional interplay between NF-κB and AR in bladder cancer cells, further indicating the difficulty in deciphering the effects of CpdA on the growth of urothelial tumor cells only through GR signaling." (PMID 30518063, 2018). "We also previously demonstrated activation of ELK1 by androgen-mediated AR signals in bladder cancer cells, as well as a significant association between the expression levels of p-ELK1 and AR in bladder tumor tissue specimens." (PMID 29518027, 2018). "It has been shown that androgen and androgen receptor stimulate malignant behavior in bladder cancer cells in vitro and in vivo." (PMID 28141864, 2017). "Further prospective cohort studies of anti-AR treatment in patients with bladder cancer are thus encouraged." (PMID 28241422, 2017). "We therefore conducted this meta-analysis of previous studies demonstrating the expression of AR, ERα, and ERβ in bladder cancer specimens." (PMID 28362839, 2017). "Remarkably, pharmacological inhibition of LSD1 resulted in significant decreases in the growth and androgen-induced AR transcription in bladder cancer cells." (PMID 28241422, 2017). "Specifically, androgens have been shown to promote bladder tumorigenesis, as well as bladder cancer cell proliferation, migration, and invasion, via the AR pathway." (PMID 28362839, 2017). "The gender-specific difference in the incidence of bladder cancer as well as AR expression in benign and cancerous urothelium suggests the involvement of AR signaling in urothelial tumorigenesis." (PMID 28241422, 2017). "These included a discrepancy in, for instance, AR positivity between bladder cancer tissues obtained at different institutions but stained at one institution using the same antibody and staining protocol." (PMID 28362839, 2017). "We therefore conducted this meta-analysis to assess the clinicopathological impact of the expression of androgen receptor (AR) and estrogen receptors (ERs) in bladder cancer." (PMID 28362839, 2017). "In AR-positive bladder cancer cells, androgens have also been shown to activate β-catenin/Wnt signaling." (PMID 28241422, 2017). "Short CAG repeat lengths (20 in UMUC3 and 22 in TCCSUP) were also identified in two AR-positive human bladder cancer cell lines." (PMID 28241422, 2017). "Accordingly, AR knockdown as well as treatment with AR antagonists inhibited the cell proliferation of bladder cancer lines cultured with androgens." (PMID 28241422, 2017). "In AR-positive bladder cancer cells, androgens are able to modulate the expression or activity of various molecules/pathways." (PMID 28241422, 2017). "Prognostic values of AR expression in bladder cancer patients have also been assessed, and the findings remain controversial." (PMID 28241422, 2017). "Subsequently, BBN was found to fail to induce bladder cancer in male or female AR knockout (ARKO) mice." (PMID 28241422, 2017). "Kawahara and colleagues recently published a paper describing a series of in vitro and in vivo experiments in AR-positive and AR-null bladder cancer models." (PMID 28085048, 2017). "Accordingly, further mechanistic studies are required to determine the precise functional role of AR signaling in the development and progression of bladder cancer." (PMID 28241422, 2017). "Recent in vitro studies have suggested a correlation between AR activity in bladder cancer cells and chemosensitivity." (PMID 28241422, 2017). "Current evidence indicating correlations of AR activation with the promotion of urothelial tumorigenesis and tumor progression supports that bladder cancer is a member of endocrine-related tumors." (PMID 28241422, 2017). "In summary, we assessed the expression status of AR, ERα, and ERβ in bladder cancers and its potential role as prognosticators." (PMID 28362839, 2017).
bladder cancer (continued). "Using cell viability or colony formation assays, androgens have been shown to induce the growth of AR-positive bladder cancer cells." (PMID 28241422, 2017). "al. showed that AR activation induces chemoresistance in bladder cancer, possibly by modulating NF-κB." (PMID 27690298, 2017). "Studies have also implicated AR in modulating various other oncogenic signaling pathways (e.g., EGFR, ERBB2, β-catenin), offering more evidence for the importance of AR-signaling as it pertains to bladder cancer biology." (PMID 28085048, 2017). "They found that DHT increased AR-positive bladder cancer cell line viability and migration in culture, while AR antagonists (i.e., hydroxyflutamide, bicalutamide and enzalutamide) inhibited viability and migration." (PMID 28085048, 2017). "Of note, androgen was recently shown to reduce sensitivity of AR-positive bladder cancer cells to doxorubicin, an anthracycline anti-tumor antibiotic often used for intravesical chemotherapy to prevent tumor recurrence." (PMID 27322140, 2016). "Meanwhile, emerging evidence has indicated the involvement of androgen-mediated androgen receptor (AR) signals in bladder cancer progression." (PMID 27322140, 2016). "In the current study, we provide preclinical evidence indicating that AR activation solely results in induction of CDDP resistance in bladder cancer cells." (PMID 27322140, 2016). "This new AR transgenic mouse line mimics certain features of human bladder cancer and can be used to study bladder tumorigenesis and for drug development." (PMID 26862755, 2016). "A previous study also demonstrated that addition of dihydrotestosterone in androgen-depleted culture medium resulted in reduction of the cytotoxic effect of doxorubicin on AR-positive bladder cancer cell proliferation." (PMID 27322140, 2016). "We observed that conditional expression of the AR in bladder urothelium significantly enhances BBN-induced bladder cancer development in both male and female mice." (PMID 26862755, 2016). "To directly address the promotional role of the AR in bladder cancer initiation and progression, we generated R26hARLoxP/+:Upk3aGCE/+ mice." (PMID 26862755, 2016). "In conclusion, we demonstrate preclinical evidence indicating that AR activation contributes to CDDP resistance in bladder cancer cells presumably via NF-κB activation." (PMID 27322140, 2016). "To further investigate the involvement of AR signals in CDDP resistance in bladder cancer cells, we established “CDDP-resistant (CR)” sublines by long-term culture with low/increasing doses of CDDP." (PMID 27322140, 2016). "In bladder cancer specimens, there was a strong trend to correlate between AR positivity and chemoresistance." (PMID 27322140, 2016). "For instance, we have demonstrated activation of ERBB2 and ELK1, both of which have also been shown to induce CDDP resistance, by androgens in AR-positive bladder cancer cells." (PMID 27322140, 2016). "Androgen blockage by flutamide in vitro as well as in vivo in mouse xenograft models with human AR-expressing bladder cancer cell lines attenuated proliferation and tumor growth [S56]." (PMID 25595907, 2015). "It has been shown that AR can increase expression and activity of EGFR and a protein encoded by the ERBB2 (also known as Her2) gene, implying androgen-mediated bladder cancer tumorigenesis and clinical progression via the regulation of the EGFR/ERBB2 pathways." (PMID 26347776, 2015). "These available data thus support that targeting androgens or AR provides effective therapeutic approaches for advanced bladder cancer." (PMID 26342199, 2015). "We demonstrated that androgen upregulated the expression of EGFR and ERBB2 as well as the levels of phosphorylation of their downstream proteins AKT and extracellular signal-regulated kinase- (ERK-) 1/2 via the AR pathway in bladder cancer cells." (PMID 26770009, 2015).
bladder cancer (continued). "In this paper, we review the evidence of inflammatory mediators and the relationship of AR and GR isoforms as they relate to the propensity for bladder cancer." (PMID 26347776, 2015). "This disparity has raised the possibility of the androgen receptor (AR) pathway being involved in the genesis of the disease; indeed, research has shown that AR is involved in and is likely a driver of bladder cancer." (PMID 26347776, 2015). "It is thus possible that ELK1 and AR serve each other as transcriptional coactivators in bladder cancer cells." (PMID 26342199, 2015). "The AR plays essential roles in carcinogenesis and metastases, most notably in prostate and bladder cancers." (PMID 26461474, 2015). "Accordingly, ELK1 inhibition, together with AR inactivation, has the potential of being a therapeutic approach for bladder cancer." (PMID 26342199, 2015). "Several animal studies have shown that androgen and androgen receptor (AR) signaling promotes whereas estrogen inhibits bladder cancer development induced by N-butyl-N-(4-hydroxybutyl)nitrosamine (BBN)." (PMID 25596734, 2015). "Accordingly, not only AR or ELK1 signaling but also their interaction offers a therapeutic target for bladder cancer." (PMID 26342199, 2015). "In AR-positive bladder cancer cell lines, dihydrotestosterone treatment increased ELK1 expression (mRNA, protein) and its nuclear translocation, ELK1 transcriptional activity, and c-fos expression, which was restored by an anti-androgen hydroxyflutamide." (PMID 26342199, 2015). "C-myc promotes tumor growth through AR signaling in a variety of AR-related cancers, such as prostate, breast, and bladder cancers." (PMID 26397136, 2015). "Recent preclinical evidence also suggests the involvement of androgen receptor (AR) signaling in bladder cancer progression." (PMID 26342199, 2015). "In the current study, ELK1 silencing in AR-positive bladder cancer lines cultured with androgen resulted in significant decreases in cell migration and invasion as well as the expression and enzymatic activity of MMP-2/MMP-9." (PMID 26342199, 2015). "Androgen-induced AR activation has been demonstrated to correlate with the promotion of bladder cancer progression." (PMID 26342199, 2015). "In particular, we and others have demonstrated the data indicating the promotion of bladder cancer growth by androgen-mediated androgen receptor (AR) activation." (PMID 26342199, 2015). "The following are key molecules that androgens/estrogens have been shown to up- or downregulate via the AR/ER pathways in bladder cancer cells." (PMID 26770009, 2015). "Using an animal model for bladder cancer, β-catenin was shown to induce tumorigenesis, and androgen-mediated AR signals appeared to synergize with β-catenin." (PMID 26770009, 2015). "We therefore decided to further study ELK1 as a potential target of androgen/AR signals in bladder cancer." (PMID 26342199, 2015). "Several proteins, including the AR which is found in both bladder stromal cells and the urothelium, are known to contribute to bladder cancer growth." (PMID 26347776, 2015). "In this study, we aim to investigate the functions of ELK1 in bladder cancer growth and their regulation by AR signals." (PMID 26342199, 2015). "To identify downstream targets of AR signals regulated by androgens in bladder cancer cells, we first screened 96 known transcription factors, using a profiling array kit." (PMID 26342199, 2015). "In xenograft models, AR knockdown in implanted bladder cancer cells suppressed AR-positive bladder tumor growth, indicating that AR is a potential therapeutic target for the treatment of bladder cancer." (PMID 23599788, 2013). "Consistent with previous findings shown by others and us androgens promoted AR-positive bladder cancer cell proliferation that was blocked by antiandrogens." (PMID 22922989, 2012). "We next assessed the effect of EGF, in conjunction with androgen and/or antiandrogen, on AR transcriptional activity in bladder cancer cells." (PMID 22922989, 2012).
bladder cancer (continued). "Taken together with our previous findings, crosstalk between EGFR and AR pathways can play an important role in the progression of bladder cancer." (PMID 22922989, 2012). "Recent animal studies further implicate a specific role for androgens and the androgen receptor in bladder cancer." (PMID 23284679, 2012). "Current results, thus, suggest that EGF promotes bladder cancer cell proliferation via modulation of AR signals." (PMID 22922989, 2012). "Additionally, AR knockdown in bladder cancer cell lines demonstrated decreased proliferation and migration." (PMID 41463239, 2025). "The potential role of AR in bladder cancer development was described as early as 1975." (PMID 41228208, 2025). "Still, a meta-analysis revealed that AR levels were positively correlated with the tumor grade of bladder cancer, but not with susceptibility or tumor stage." (PMID 41228208, 2025). "Furthermore, androgen depletion in AR-positive human bladder cancer cells in vitro, or castration in mice, inhibited tumor cell growth, as did the AR knockdown." (PMID 41228208, 2025). "Moreover, AR regulated the immune response to tumors in bladder cancer by downregulating PD-L1 by directly binding to AR response elements of the PD-L1 promoted region and increasing CD8+ lymphocyte activity." (PMID 40612952, 2025). "Nonetheless, similar inhibitory effects of dutasteride on the cell growth, as well as the expression of oncogenic proteins including β-catenin, Bcl-2, MMP2, MMP9, NF-κB, and p21, were seen in AR-negative bladder cancer lines, suggesting the involvement of the non-AR pathway." (PMID 40486871, 2025). "Consistent with a tumor suppressor role of androgens and/or AR in bladder cancer, the absence of AR expression was associated with recurrence in non-muscle-invasive bladder cancer." (PMID 41228208, 2025). "Whether the possible tumor suppressor role of AR and/or androgen explains the disadvantage of female survival in bladder cancer warrants further investigation." (PMID 41228208, 2025). "AR expression was detected in only a subset of bladder cancer cell lines and bladder tumors." (PMID 41228208, 2025). "AR mRNA expression has been assessed in bladder cancer tissues." (PMID 40486871, 2025). "Additionally, in animal studies using heterotopic or orthotopic xenograft models or transgenic mouse models for bladder cancer, surgical or medical castration, as well as treatment with anti-AR agents, impaired the growth of tumors." (PMID 40486871, 2025). "Similarly, using in vitro models, androgens have been shown to promote the proliferation, migration, and invasion of AR-positive bladder cancer cells, while anti-androgen treatment or AR knockdown results in their retarded growth." (PMID 40486871, 2025). "Moreover, AR expression was found to be considerably elevated in bladder cancer sublines resistant to cisplatin or gemcitabine therapy, and radiotherapy." (PMID 40486871, 2025). "In addition, knockdown and overexpression of AR in bladder cancer lines resulted in an increase and a decrease, respectively, in the expression of PD-L1." (PMID 40486871, 2025). "In addition, a long non-coding RNA, FAM83H-AS1, was shown to be up-regulated in bladder cancers, while AR induced its expression in prostate cancer cells." (PMID 40486871, 2025). "In our study, AR-FL mRNA levels were lower in bladder cancer." (PMID 39083104, 2024). "Additionally, FKA likely exerts an anti-angiogenic effect by downregulating the androgen receptor in bladder cancer to some extent, resulting in a more pronounced reduction in tumor growth in male transgenic mice compared to females." (PMID 38611849, 2024). "Androgen receptor (AR) signaling is crucial in bladder cancer pathogenesis." (PMID 38398136, 2024). "According to our results AR-FL protein is increased in bladder cancer." (PMID 39083104, 2024). "Thus, DHT-mediated the activation of AR signaling is considered as an attractive target for the management of bladder cancer in male patients." (PMID 39680264, 2024).
bladder cancer (continued). "AR-FL protein positivity was 65% in bladder cancer group and 0% in control group." (PMID 39083104, 2024). "Key future directions will assess anti-androgens for secondary chemoprevention, as part of a combination approach with bladder-cancer-directed immunotherapies, and whether AR pathway and T-cell functional biomarkers can predict therapeutic outcomes." (PMID 38398136, 2024). "This is the first study to measure AR-FL protein levels in bladder cancer patients with WB." (PMID 39083104, 2024). "Owing to a growing and compelling body of work linking the AR to bladder cancer, anti-androgens may play an integral role in the next generation of bladder cancer therapies." (PMID 38398136, 2024). "The contribution of AR-FL to bladder cancer has been well-proven in pre-clinical studies." (PMID 39083104, 2024). "DHT, as an androgen, may function by binding with nuclear androgen receptor (AR) to promote the development of bladder cancer." (PMID 39680264, 2024). "Based on the data, reducing bladder cancer invasion may be achieved by inhibiting AR, and anti-androgen Enzalutamide can reduce bladder cancer cell invasion." (PMID 38283839, 2023). "More fascinatingly, AR activity has also been associated with sensitivity to conventional nonsurgical treatments for bladder cancer, including CDDP-based chemotherapy." (PMID 37762034, 2023). "Research has shown that the presence of the androgen receptor (AR) gene, which is situated on the X chromosome (Xq11-12), could potentially explain the differences in bladder cancer occurrence across genders." (PMID 38283839, 2023). "Thus, GABBR2 expression was correlated with the expression and activity of AR in bladder cancer cells." (PMID 37762034, 2023). "In an experimental mouse model, the knockout of AR could offset the incidence of bladder cancer induced by chemical carcinogen." (PMID 35053220, 2022). "Additionally, the XIST/miR-124/AR axis in bladder cancer has been shown to upregulate the expression of proliferation-associated factors, c-myc and p27, and metastasis-associated factors, MMP9 and MMP13." (PMID 36362406, 2022). "Although androgen receptor (AR) can influence bladder cancer (BCa) initiation and progression, its impact on tumor immune escape remains unclear." (PMID 35915245, 2022). "As such, the activation of ERα could promote the proliferation of bladder cancer cells, whereas ERβ and AR could promote bladder cancer growth and invasion via the alteration of tumour suppressor gene expression." (PMID 36011004, 2022). "Treatment with DHT in AR-positive bladder cancer cells induces the expression of p-ERK and also induces the expression of p-ATF2, but if any change in ATF2 protein expression is observed, these effects could be antagonized by HF." (PMID 33919565, 2021). "Our previous study additionally indicated that ERK could be activated by AR in bladder cancer cells." (PMID 33652650, 2021). "Inactivated AR signaling inhibits bladder cancer tumorigenesis via autophagy." (PMID 33919565, 2021). "More interestingly, AR activation has been linked to resistance to conventional non-surgical treatments for bladder cancer, including CDDP therapy, as well as intravesical bacillus Calmette-Guѐrin immunotherapy and radiotherapy." (PMID 34576193, 2021). "Based on the common origin, a hypothesis has been proposed that AR signaling is involved in the carcinogenesis of bladder cancer." (PMID 33919565, 2021). "In AR-positive bladder cancer cells, DHT could activate the epidermal growth factor receptor (EGFR)/ERBB2/ERK pathway in the presence of the epidermal growth factor (EGF)." (PMID 33919565, 2021). "Meanwhile, AR activation in bladder cancer cells has been suggested to induce chemoresistance." (PMID 33652650, 2021). "Interestingly, our recent observations have suggested that AR activity in bladder cancer cells correlates with sensitivity to other conventional non-surgical treatments, such as intravesical BCG immunotherapy and radiotherapy." (PMID 33652650, 2021).